EGFR (epidermal growth factor receptor)
Diseases named in the same sentence as EGFR in open-access papers (continued):
Sharing a sentence is not in itself a finding about the gene and the disease.
brain tumors (continued). "We therefore investigated whether anti-EGFR mAb might reduce the number of CSC from this brain tumour." (PMID 19293809, 2009). "Additionally, in human brain tumor specimens, FABP7 expression has been shown to be associated with epidermal growth factor receptor (EGFR) overexpression." (PMID 19014610, 2008). "In addition, because the EGFR–AXL complex has been detected in brain tumor cells, and EGFR can form heterodimers with HER2 and HER3, LDOC1 may also affect cellular transport, including internalization and PM recycling of these EGFR-interacting partners." (PMID 38338651, 2024). "No relation between TCR status and EGFR mutation was found either in lung or brain tumor." (PMID 33479213, 2021). "PLEKHA5 facilitates cell migration and invasion and is linked to brain tumor metastasis via the PI3K-AKT pathway, whereas ST3GAL5 encodes a sialyltransferase that catalyzes the formation of ganglioside GM3, a suppressor of EGFR/PI3K-AKT signaling and cell proliferation, and a inducer of apoptosis." (PMID 29587824, 2018). "The restriction of EGFRvIII expression to EGFR amplified brain tumors supports this hypothesis." (PMID 25658924, 2015). "Brain tumour patients could also benefit from combining adoptive transfer of NK cells with already approved therapeutic antibodies such as cetuximab, an anti-epidermal growth factor receptor (EGFR) antibody." (PMID 24085644, 2014). "CAR-T cells, engineered to recognize tumor-associated antigens (TAAs) such as IL13Rα2, HER2, epidermal growth factor receptor (EGFR)/EGFRvIII, and B7-H3, have shown promise in GBM and pediatric brain tumors." (PMID 40948940, 2025). "In the “FDA-approved different tumor type” category, brain tumors were the most common cancer category (n = 16, 25.0%) with PD-1/PD-L1 inhibitors (n = 6, 38%), CDK4/6 (n = 3, 19%), and EGFR (n = 3, 19%) inhibitors the most common treatments." (PMID 38461318, 2024). "The development of bispecific antibodies targeting HER2 or EGFR and CD3 offers new perspectives for immunotherapy in solid tumors, including brain tumors." (PMID 39199683, 2024). "In the context of human brain tumors, EGFR is overexpressed in a subset of GBM and MB, and EGFR targeting is a promising approach for the NPs’ delivery." (PMID 36839827, 2023). "As previously reported, EGFR/MAPK signaling can inhibit the invasion and migration of more than one tumor of the brain." (PMID 37971595, 2023). "Here, we assessed EGFR gene amplification using FISH and Infinium Methylation EPIC Bead Chip analysis—a technique that is routinely used for molecular brain tumor classifications." (PMID 35453544, 2022). "EGFR, RAS, and B-Raf mutants all enhance this PKM2 function that is critical for successful cell divisions and brain tumor progression." (PMID 36198360, 2022). "In this study, we demonstrate that PFKP promotes EGFR activation-induced VEGF expression in HIF-1α-dependent and -independent manners in GBM cells, leading to enhanced blood vessel formation and brain tumor growth." (PMID 36435833, 2022). "A novel algorithm was designed to simulate VEGFR inhibitor effects on blood vessel growth and was integrated into a multiscale model of brain tumors based on the VEGFR signaling pathway and the EGFR signaling pathway (Eqs." (PMID 31074391, 2019). "The overexpression of EGFR and HER-2 in different types of canine malignancies, such as mammary gland tumors, osteosarcoma, gastric tumors, and brain tumors, has been reported." (PMID 31610784, 2019). "The developed multiscale model revealed angiogenesis-induced drug resistance mechanisms of brain tumors to EGFRI treatment and predicted a synergistic drug combination targeting both EGFR and VEGFR pathways with optimal combination timing." (PMID 31074391, 2019). "Western blot analyses of in vivo‐treated tumors revealed that treatment with osimertinib efficiently inhibited the phosphorylation of EGFR and that of its downstream molecule, ERK, in both brain tumor and subcutaneous tumor models." (PMID 29125233, 2017).
brain tumors (continued). "Another currently targeted protein in brain tumors is STAT3, a molecule that is downstream of several oncogenic signaling cascades in glioma, including EGFR and PDGF receptor." (PMID 28003994, 2016). "Using IHC to identify GBM, we demonstrated that the EGFR (lower-left panel), and the astrocytic marker, GFAP (lower-right panel) were present in brain tumor sections." (PMID 27285755, 2016). "To investigate the composition of NHERF1 protein complexes in ependymoma, we screened the intracellular localization of the NHERF1 ligands moesin, NF2, PTEN, PDGFRα, EGFR, YAP1, β-catenin and PHLPP2 that have been functionally involved in primary brain tumors." (PMID 25775275, 2015). "Results illustrate that VBLs increased the specific intracellular labeling of EGFR by 50%, and, importantly, significantly bypassed Qdot entrapment within endosomes for the GBM and MB brain tumor samples studied." (PMID 22339792, 2012). "Notably, important oncogenes involved in brain tumor development are located on these chromosomes, such as PDGFR1 and FGFR2 on chromosome 4, EGFR and MET on chromosome 7, and CDK4 and MDM2 on chromosome 12." (PMID 41323387, 2025). "Several studies investigated the expression level of EGFR protein in patients with brain tumour, using different antibodies, most of which were not wtEGFR specific and cross-react with EGFRvIII, and different scoring systems." (PMID 40227788, 2025). "EGFR was diffusely expressed in 100% of gliomatosis cerebri cases (average intensity 3.7/4) and in 25%–40% of other brain tumors at lower intensity, while absent in control brains." (PMID 39473196, 2024). "EGFR, PDGFRA and CD44 are potential TAA for brain tumor therapy." (PMID 39473196, 2024). "Cloned almost forty years ago, the interest in EGFR's structure/function relationships remains unabated, not least because changes in oncogenic EGFR mutants are key drivers of the formation of lung and brain tumours." (PMID 36282005, 2023). "The results provide preliminary evidence that AZD-9291 has a tolerable safety profile in patients with brain tumors and may benefit patients with recurrent GBM and EGFR alterations." (PMID 38115126, 2023). "Concerning EGFR and PI3Kp110β inhibition models, they represent pioneering efforts in the data mining field since no targeted drug for brain tumors elected by regression QSAR models met the conditions to achieve clinical trials." (PMID 35884571, 2022). "In the preclinical study, osimertinib showed greater BBB penetration compared to previous generation EGFR-TKIs and exhibited sustained metastatic brain tumor regression in mouse and nonhuman primate models." (PMID 34359582, 2021). "In the example of EGFR as a biomarker in another brain tumor type, GBM, its characterization was based on the retrospective analyses of relationships between treatment outcomes and EGFR gene expression in 87 newly diagnosed patients with GBM who were enrolled in clinical trials." (PMID 34768783, 2021). "The epidermal growth factor receptor (EGFR) is over-expressed by most brain tumors, but not by normal tissues, which explains the reason why cetuximab (CET), the EGFR monoclonal antibody, was developed specifically for brain tumor targeting." (PMID 32993166, 2020). "Overexpression of the epidermal growth factor receptor (EGFR), which plays an important role in cell growth and development through the cell cycle pathway, is shown to be common and correlated with tumor grade in pediatric brain tumors." (PMID 27613841, 2016).
brain tumors (continued). "In our study, although DHAO feeding increased FABP7 mRNA levels of rat's brain tumors, it did not affect EGFR expression." (PMID 19014610, 2008). "A recent discovery has established that circ-EGFR deprivation not only suppresses tumorigenicity in brain tumor-initiating cells but also enhances the efficiency of nimotuzumab in the treatment of GBM, suggesting a compelling link between circ-EGFR and treatment efficacy in cancers." (PMID 41214390, 2025). "Analysis of the cell surfaceome in pediatric and adult tumors revealed EphA3 as a prominent cell surface protein across various brain tumor subtypes, especially in the context of comparison to existing immunotherapeutic targets in clinical development EphA2, HER2, CD276, CD70, and EGFR." (PMID 39111833, 2024). "EGFR is simultaneously overexpressed in most brain tumors but not expressed in normal tissues." (PMID 36145722, 2022). "This indicated that specific T cell expansion in brain tumor might play a positive role in TKI response in EGFR-mutant LUAD, but a negative role in other conditions." (PMID 33479213, 2021). "In this study, we demonstrate that PFKP plays an instrumental role in EGFR activation-induced β-catenin transactivation in a PFKP Y64 phosphorylation-dependent manner, thereby regulating migration, invasion, and proliferation of GBM cells and brain tumor growth." (PMID 32195176, 2020). "As EGFR and HGFR were highly activated in pediatric brain tumors and subsequently high percentages of pediatric brain tumor cells expressed these RTKs, these findings could provide a rational explanation of the limited efficacy of single targeted treatment in clinical trials." (PMID 25799134, 2015). "Interestingly, further analysis revealed that the xenograft tumor we tested in vivo (X1016) also has amplification of EGFR (unpublished data from G.Y.G, UAB Brain Tumor Core Facility) in addition to high levels of activated STAT3 and NF-κB, suggesting a probable classical genetic subtype." (PMID 24244348, 2013). "EGFR is expressed not only in tumors but also in normal epithelia; therefore, it may not always be feasible to target brain tumors with EGFR." (PMID 23304519, 2012). "Moreover, nimotuzumab, a monoclonal antibody against the epidermal growth factor receptor (EGFR) with a potent antiangiogenic activity, has been shown by our group to reduce the frequency of CSC-like subpopulations in mouse models of brain tumors when combined with ionizing radiation." (PMID 24212957, 2011). "Our data suggest that, for metastatic brain tumors positive for EGF family receptors, such as HER2 or EGFR, PDE5 inhibitors may offer a possibility of efficacious treatment using pertinent antibodies (trastuzumab and cetuximab, respectively) that are otherwise inefficient." (PMID 20419092, 2010). "Further clinical investigations are needed to assess the efficacy and safety of osimertinib in this brain tumor population, particularly in patients whose tumors express EGFR vIII rearrangements, and to identify which EGFR alterations may sensitize tumors to this BBB penetrant EGFR-TKI." (PMID 35601813, 2021). "Importantly, we showed that EGFR-phosphorylated PFKP Y64 has a critical role in AKT activation and AKT-mediated β-catenin S552 phosphorylation and subsequent β-catenin transactivation and promotion of tumor cell glycolysis, migration, invasion, proliferation, and brain tumor growth." (PMID 32195176, 2020). "Interestingly, EGFR overstimulation by itself is not enough to drive brain tumor formation." (PMID 24381541, 2013). "The mechanisms of macrophage/microglia ADCC against brain tumors are not well documented, nonetheless a study from the 90's demonstrated microglia ADCC using an anti-EGFR mAb." (PMID 24127551, 2013).
brain tumors (continued). "EGFR was found no relation with TMB, CD8+ TILs, or PD-L1 expression either in lung or brain tumor." (PMID 33479213, 2021). "In our previous studies evaluating the role of EGFR in the treatment of brain tumors, we also observed that 11 HGG cells expressed more EGFR at the cell surface compared to 15 cell culture, but receptor expression level was not correlated with the response to EGFR inhibition treatment." (PMID 31547056, 2019).
oral cancer (203 papers, 2003 to 2026). "Our study provides evidence that the concurrent expression of EGFR and Mcl-1 is linked to a poor prognosis in oral cancer patients." (PMID 38888847, 2025). "EGFR overexpression is associated with poor prognosis in oral cancer, contributing to a malignant phenotype characterized by inhibited apoptosis and enhanced metastatic potential." (PMID 40699851, 2025). "Taken all together, COX-2/PGE2 signaling axis is linked to oxidative damage, inflammation, and epidermal growth factor receptor signaling, making targeting them a promising strategy for oral cancer treatment." (PMID 39937256, 2025). "This is an important fact that shows that the more carefully designed studies are able to better demonstrate the association between EGFR overexpression and poor prognosis in oral cancer." (PMID 37569265, 2023). "Various oncogenes have been implicated in oral cancer development, including the epidermal growth factor receptor (EGFR/c-erb 1), members of the Ras gene family, c-myc, int-2, hst-1, PRAD-1, and bcl-1." (PMID 37375955, 2023). "The proposed mechanism of therapeutic resistance to EGFR TKIs include constant stimulation of downstream signaling pathways by mutated RAS gene in oral cancer via special group of genes such as CCND1, c-MYC, BCL-XL and BCL-2." (PMID 35047986, 2020). "Two classes of new therapeutic agents directed against molecules involved in apoptosis pathway have been developed that can be used in combination with anti-EGFR therapy in oral cancers to overcome EGFR polymorphism based therapeutic resistance." (PMID 35047986, 2020). "A recent analysis revealed that about 2.8% of oral cancers carry mutations in the tyrosine kinase domain of EGFR." (PMID 35047986, 2020). "We carried out this study to evaluate mutational profile of tobacco associated oral carcinoma with special emphasis on EGFR and its downstream events." (PMID 31775759, 2019). "Additional studies are needed to assess the impact of geriatric assessment in patients receiving oral cancer treatment, more particularly EGFR TKIs and also to identify geriatric parameters associated with tolerance and/or survival." (PMID 29492192, 2018). "The unfavorable clinical outcome of oral cancer is often associated with aberrant activation of epidermal growth factor receptor (EGFR) signaling." (PMID 29849877, 2018). "Recent studies suggest that overexpression of EGFR results in poor prognosis in oral cancer and its activation is associated with malignant phenotype, inhibition of apoptosis and increased metastatic potential." (PMID 25918252, 2015). "Immunostaining showed a significant association between EGFR expression and aberrant accumulation of β-catenin in oral cancer." (PMID 20302655, 2010). "Similarly, loss of LCN2 in oral cancer cell lines leads to a decrease in EGFR recycling and a decrease in invasion." (PMID 40356520, 2025). "Therefore, in the present study, we aimed to investigate the clinical significance of EGFR-TKIs as an anticancer drug candidate and to elucidate the molecular mechanism underlying its anticancer activity in human oral cancer." (PMID 38888847, 2025). "It then focuses on combinatorial approaches that target microtubules, as well as various signaling pathway components implicated in oral cancer progression, namely, DNA repair players, the epidermal growth factor receptor, cyclin-dependent kinases, epigenetic readers, and immune checkpoint proteins." (PMID 37376101, 2023). "EGFR is associated with oral cancer development and chemoresistance." (PMID 35402265, 2022). "EGFR has been earlier implicated in progression, recurrence, and stemness of oral cancer." (PMID 33317464, 2020).